SUB1 (SUB1 regulator of transcription)
Diseases named in the same sentence as SUB1 in open-access papers (continued):
Sharing a sentence is not in itself a finding about the gene and the disease.
tumor (10 papers, 2016 to 2025). "The knockdown of CD74 or SUB1 suppresses tumor growth, and HGF has shown potential as a therapeutic target due to its role in fibrosis reversal and lung repair." (PMID 40136480, 2025). "To demonstrate the role of SUB1 on tumor growth in vivo, we used a chick chorioallantoic membrane (CAM) assay and measured spontaneous metastasis, including local invasion, intravasation and metastasis to distant organs." (PMID 27270442, 2016). "Both SUB1-shRNA 1 and 2 cells showed significantly reduced tumor growth and tumor weight in mice relative to control animals, demonstrating that SUB1 inhibition attenuates tumor growth (CAM assay and murine xenografts) and metastasis (CAM assay) in vivo." (PMID 27270442, 2016). "Furthermore, there was attenuation of tumor metastasis in the SUB1 knockdown group compared with the control group." (PMID 27270442, 2016). "Prior studies have shown that SUB1 is upregulated in GBM and enhances tumor cell proliferation and migration." (PMID 41020875, 2025). "CD74, HGF, and SUB1 are frequently overexpressed in NSCLC, promoting tumor proliferation and survival." (PMID 40136480, 2025). "We also extensively survey TF-RBP crosstalk, highlighting how SUB1, a previously uncharacterized RBP, drives aberrant tumor expression and amplifies the effect of MYC, a well-known oncogenic TF." (PMID 32728046, 2020). "In particular, we found that TMEM30A regulates several migration-related genes including SUB1, SLC2A1, CTNNB1, ACTB, and CLTC during tumor migration, which further demonstrates the effectiveness of our proposed method." (PMID 28640862, 2017). "Interestingly, RNA expression in tumor tissue was only evident for CEACAM1, MAGEA4, SRC, TPBG, GPA33, and SUB1, with the highest and lowest expression for SRC and MAGEA4, respectively." (PMID 39949781, 2025). "Depletion of SUB1 resulted in significantly reduced tumor weight compared with non-target short hairpin RNA (shRNA)-transfected control cells." (PMID 27270442, 2016). "Resting tumour cDC1s included cluster 5 enriched in transcripts involved in the unfolded protein response (UPR) such as Creld2, Hspa5, and Pdia6, as well as the clusters 2, 3 and 6 that expressed transcripts such as Fos, Jun, and Dusp1 and cluster 0 that expressed H2afz, Lyz2, Sub1." (PMID 40745918, 2025).
cancer (9 papers, 2015 to 2022). A tumor composed of atypical neoplastic, often pleomorphic cells that invade other tissues. "For example, the ENCODE eCLIP profile for the RBP SUB1 has binding peaks enriched on the 3′UTR regions of genes, and the predicted targets of SUB1 were significantly up-regulated in many cancer types (left)." (PMID 32728046, 2020). "SERPINH1 and SUB1 in turn were described as oncogenes in different cancer types promoting cell proliferation and invasion." (PMID 33066457, 2020). "Expression profiling in several cancers revealed SUB1 overexpression, suggesting a potential role in tumorigenesis." (PMID 27270442, 2016). "As an RBP, SUB1 has not been associated with cancer previously, so we sought to investigate its role." (PMID 32728046, 2020). "SUB1 has been recently found to show an upregulated level in different cancers." (PMID 27270442, 2016). "Moreover, we find that up-regulation of SUB1 targets may lead to decreased patient survival in some cancer types." (PMID 32728046, 2020). "Although earlier studies showed the role of SUB1 in cancer, its mechanistic insight in oncogenesis is not fully understood." (PMID 27270442, 2016). "Another 6 genes, SUB1, SLC2A1, CTNNB1, ACTB, HSP90B1, and CLTC were selected from the remaining unknown migration-related genes in order to confirm their relationship with cancer cell migration." (PMID 28640862, 2017).
infection (5 papers, 2021 to 2025). The state of being infected such as from the introduction of a foreign agent such as serum, vaccine, antigenic substance or organism. "Genetic experiments have shown that SUB1 is indispensable for parasite survival, with SUB1 gene disruption leading in asexual blood stages and the preceding liver stages of infection to a complete block in merozoite egress." (PMID 33975947, 2021). "FOXP3 and SUB1 were successfully overexpressed in Tcon and Treg cells by infection with recombinant lentivirus." (PMID 34162888, 2021). "Since SUB1 plays an essential role in the development and release of exoerythrocytic (liver-stage) merozoites that initiate blood-stage infection, medicines based on SUB1 inhibitors have prophylactic as well as therapeutic potential." (PMID 33975947, 2021). "Additionally, a higher number of intracellular parasites were observed in ΔSUB1 cells than in the wild-type control, indicating that SUB1 silencing effectively blocked Cryptosporidium egress and infection spread." (PMID 39902829, 2025). "Research in Plasmodium falciparum has highlighted the role of Subtilisin-like serine protease 1 (SUB1) in cleaving parasite vesicle membranes (PVM) and host cytosolic membranes, promoting infection spread." (PMID 39902829, 2025).
SUB1 also shares sentences with these, for which no sentence is quoted: hepatoblastoma (2 papers); lung adenocarcinoma (2); astrocytoma (1); hepatocellular carcinoma (1); melanoma (1); prostate tumor (1); Stroke (1).